LRRC74B (leucine rich repeat containing 74B)
Tractability: No criterion of Open Targets' tractability assessment is met for any kind of drug.
Gene: Protein-coding gene on chromosome 22 (21,045,946 to 21,064,168, forward strand). Ensembl gene ENSG00000187905.
Homologues: Orthologues: chimpanzee LRRC74B (99% identical), rabbit LRRC74B (79% identical), pig LRRC74B (77% identical), guinea pig LRRC74B (74% identical), dog LRRC74B (70% identical), mouse Lrrc74b (68% identical), rat Lrrc74b (66% identical), tropical clawed frog lrrc74b (46% identical), zebrafish lrrc74b (44% identical). Paralogues in human: LRRC74A (33% identical).